OCLN (occludin)
Diseases named in the same sentence as OCLN in open-access papers (continued):
Sharing a sentence is not in itself a finding about the gene and the disease.
colitis (continued). "In parallel, the mRNA expression of Muc2, ZO-1, Occludin and Claudin4 were markedly reduced in the DSS-induced colitis mice (p < 0.05)." (PMID 40130239, 2025). "We found that the KAR treatment remarkably improved the damage of tight junctions ZO-1, Occludin, and E-cadherin in TNBS-induced colitis." (PMID 40375985, 2025). "ZO‐1, claudin‐1, and occludin were notably lower in the DSS group than in the other groups, and the colonic TJ protein levels of the colitis model mice were increased following the administration of DP7." (PMID 39896755, 2025). "The synthesis of essential tight junction proteins, including occludin, claudin-1, and ZO-1, was markedly diminished in DSS-induced colitis, as determined by qPCR examination of colonic tissue." (PMID 40725052, 2025). "In the colitis model, combined LCs supplementation significantly suppressed the expression of TNF‐α, CXCL4, and caspase‐3, while enhancing occludin expression, thereby protecting against 5FU‐induced colonic apoptosis and barrier disruption." (PMID 40444121, 2025). "In a DSS-induced colitis model, inhibition of HMGB1 was observed to increase intestinal Occludin, E-cadherin, and Claudin-1 expression in experimental mice." (PMID 40689397, 2025). "Kae was reported to increase the expression of ZO‐1, Occludin, and Claudin‐1 in DSS‐induced colitis in mice, thereby improving intestinal permeability." (PMID 40488195, 2025). "At the same time, STAT3 knockout also reduced the differences in the expression of IL-6, TNF-α, and IL-1β, as well as ZO-1, occludin, BCL-2, and BAX in the colons of mice with colitis induced by different diets." (PMID 38233383, 2024). "Colitis induction led to significantly higher macroscopic and microscopic damage scores, elevated TOS levels, reduced occludin and ZO-1 intensity, decreased mucosal thickness, and TAS levels compared to the Control group (p < 0.001)." (PMID 39105785, 2024). "And VSL#3 was also shown to increase the expression of tight junction genes, Zo-1, occludin, and claudin-1 in the colon tissue in TNBS-induced colitis mice." (PMID 39849930, 2024). "Consistent with the literature, we found that intragastric administration of DHA protects the integrity of the epithelial barrier by reducing the destruction of occludin and ZO-1 proteins, thereby showing protective effects against TNBS-induced colitis." (PMID 39105785, 2024). "Previous research has demonstrated that FICZ effectively counteracted the decrease in the expression levels of ZO-1, occludin, and claudin-1 induced by DSS in mice colitis, thereby enhancing the integrity of the intestinal barrier." (PMID 38473179, 2024). "Compared to the control group, the levels of Occludin (p < 0.05) and ZO-1 (p < 0.01) were significantly reduced in the colon of the DSS-induced colitis group." (PMID 38474831, 2024). "Supplementation with SBP significantly restored the levels of ZO-1, occludin, Muc2, Muc3, and CDX2 in the colon of colitis mice, approaching near-normal levels." (PMID 38732527, 2024). "In colitis rats, CGA promotes the assembly of epithelial tight junctions by decreasing the phosphorylation of occludin and claudin-1, thereby reducing intestinal permeability and attenuating intestinal barrier damage." (PMID 37444374, 2023). "The effects of GQD on DSS-treated colitis were examined via daily body weight, DAI, colon length, HE staining, PAS staining, ZO-1 and Occludin immunohistochemical staining." (PMID 37649073, 2023). "The results showed that the ZO-1, Occludin and Claudin-1 proteins were decreased in the intestines of DSS-induced colitis mice, and both Occludin and Claudin-1 levels were significantly restored after SCP treatment." (PMID 38004208, 2023). "Our results showed that PAS effectively inhibited inflammation and restored the colonic mucosal barrier in colitis treatment, mainly by significantly upregulating the expression of ZO1 and Occludin." (PMID 37870220, 2023).
colitis (continued). "It has previously been shown that suppressing both MAPK pathways contributed to the amelioration of chemically induced murine colitis and the restoration of the intestinal barrier by elevating tight junction expression (CLDN1, ZO-1, OCLN)." (PMID 37174625, 2023). "We found that N5 treatment enhanced tight junction proteins ZO-1 and occludin and cytoprotective HSP70 levels under physiological condition and restored their mucosal expressions in colitis (P < 0.05)." (PMID 38033603, 2023). "In a previous study, some yeasts were reported to reduce gut barrier disruption by increasing the relative expression of Occludin and ZO-1, which relieved DSS-induced colitis." (PMID 37047694, 2023). "Our results showed that DSF+Cu2+ had a protective effect on DSS-induced colitis, manifested by significantly improved body weight, colonic length, histological score, reduced DAI score, and increased expression of MUC2, ZO-1 and occludin." (PMID 37284442, 2023). "After treatment with SC-5, the expression levels of occludin, claudin-3, and ZO-1 were up-regulated compared with the DSS group (p < 0.05), indicating that SC-5 can alleviate DSS-induced colitis in mice by enhancing the expression of tight junction proteins." (PMID 36832972, 2023). "Moreover, the RT-PCR analysis further confirmed that the inosine intervention could up-regulate the transcriptional levels of ZO-1, occludin, and claudin-1 in mice with colitis, while a low dose of inosine intervention had little impact on their expression levels." (PMID 37762155, 2023). "As revealed in the Caco-2 cells as well as the colitis mice, the treatment of bioactive peptides in foxtail millet protein hydrolysate (FMPH) increased intestinal ZO-1 and Occludin expressions compared with the DSS-induced groups." (PMID 35406093, 2022). "In the present study, the mRNA expression of Occludin and ZO-1 proteins in DSS-induced colitis mice was reduced by 53.73 and 86.46%, respectively." (PMID 36033869, 2022). "Occludin also plays a complex role in the regulation of epithelial cells and immune homeostasis and is usually down-regulated in UC patients and DSS-induced colitis mouse models." (PMID 35455427, 2022). "Studies have shown that increased OCLN can maintain intestinal barrier function in patients with ulcerative colitis and mice with colitis, which is consistent with our finding that ALA increased the expression of OCLN in intestinal epithelial injury repair." (PMID 35712055, 2022). "The expression of tight junction proteins (occludin, ZO-1), HIF-1α as well as VDR was up-regulated in colitis mice with hypoxia stimulation." (PMID 35711312, 2022). "In Caco-2 monolayers and a mouse model of colitis, AGE prevented occludin, ZO-1, and microbe translocation." (PMID 36552041, 2022). "Studies have also found activation of microglial cells and decrement in occludin and claudin-5 expression in the brain tissue after DSS-induced colitis." (PMID 35011101, 2022). "Meanwhile, compared with the DSS group, the mRNA expressions of tight junction proteins, including Claudin-1 and occludin were significantly increased in PSPE and PSPc-treated colitis mice (p < 0.05)." (PMID 36358470, 2022). "Transcript levels of occludin, a tight junction protein, and TGF-β, which is induced in wound healing, remained unchanged over the course of acute colitis in all mouse groups." (PMID 36567940, 2022). "Soluble fibers have been shown to up-regulate the ZO-1 and occludin expressions in the wild-type and the occludin in the CD4+CD62L+T cell transfer model of colitis mice." (PMID 35223407, 2021). "For mice with DDS-induced intestinal damage and colitis, BER can reduce colon tissue damage, upregulate the expression of ZO-1 and occludin, upregulate the expression of antiapoptotic proteins, and downregulate the expression of apoptotic proteins." (PMID 34712727, 2021). "Expression of occludin and MPO was significantly decreased and increased, respectively, in DSS colitis mice." (PMID 34681392, 2021).
colitis (continued). "It was also reported that that expression of OCLN and CLDN3 is reduced in DSS-induced colitis compared to the control group." (PMID 34444876, 2021). "Tight junction proteins such as E-cadherin, occludin, and claudin-3 are involved in barrier function in the intestine, and their low expression levels are closely related with DSS-induced colitis." (PMID 34899643, 2021). "The expression levels of two key tight junction proteins, ZO-1 and occludin, were dramatically decreased in the DSS-induced colitis mice compared to the CTRL group." (PMID 34395495, 2021). "This connection between ClC-2, occludin, and caveolin-1 was further supported in vivo with a model of DSS-induced colitis." (PMID 32024112, 2020). "We also investigated the effect of sinapic acid on the protein levels of claudin-1, occludin, and ZO-1 in the colon of the DSS-induced colitis mice." (PMID 33312339, 2020). "It was also observed that sinapic acid also enhanced the protein levels of occludin, ZO-1, and claudin-1 to maintain the normal function of the intestinal barrier in DSS-induced colitis in mice." (PMID 33312339, 2020). "In a previous study, the expression of claudin-1 and occludin, important indicators of the integrity of the intestinal mucosal barrier, were inhibited in DSS-induced colitis." (PMID 33240279, 2020). "We observed that the expressions of tight junction proteins, such as claudin-1, occludin, and E-cadherin remarkably reduced in the colonic tissues of DSS induced colitis mice by Western-Blot." (PMID 30708992, 2019). "After EPS-1 administration, the reduced expressions of claudin-1, occludin, and E-canherin proteins were counteracted, which provided another powerful evidence for the protective effects of EPS-1 on mice colitis." (PMID 30708992, 2019). "Compared with the normal group, the expressions of the TJs were significantly reduced in the colitis group (P < 0.01 for JAM-1, P < 0.001 for occludin, and P < 0.001 for claudin-4)." (PMID 29849501, 2018). "Consistently, our data showed that the expression of occludin and ZO-1 was decreased notably in DSS-induced mouse colitis." (PMID 30393231, 2018). "In a study of experimental colitis in mice, anti-TNF drugs, such as infliximab and etanercept, attenuated inflammation induced reductions in ZO-1 and occludin." (PMID 30127744, 2018). "Oral administration of recombinant L. lactis expressing pIGF-I3 attenuated DSS-induced colitis and protected intestinal function by improving CDS, MPO and DAO activities, and inhibiting the increase of colonic occludin level." (PMID 26932768, 2016). "Consistent with the in vitro experiment, we showed that BS administration recovered expression or distribution of tight junction proteins, ZO-1, Occludin, and Claudin-1, in DSS-induced colitis." (PMID 27912750, 2016). "It was found that the administration of HQT increased occludin and ZO-1 expression in DSS-induced colitis model." (PMID 27982094, 2016). "In line with our results, previous studies reported a disrupted and irregular expression pattern of tight junction proteins including occludin and claudin-4 in the colonic mucosa in mice with DSS-induced colitis." (PMID 26218284, 2015). "In addition, PDTC leads to an upregulated expression of occludin and zonulin-1 in mice with DSS colitis." (PMID 41233883, 2025). "Eliminating Akt1 from human IECs in vitro resulted in greater expression of occludin and claudin 4, and mice lacking GC-C exhibited lower levels of occludin and claudin-4, intestinal hyperpermeability and susceptibility to DSS-induced colitis." (PMID 40801095, 2025). "Similarly, in this study, the protein levels of tight junction proteins in colon tissue, such as ZO-1, occludin, and claudin-1, were down-regulated in the DSS-induced colitis mice." (PMID 41010526, 2025). "The rTsASP2 could directly degrade the TJ proteins Occludin and Claudin-1, thereby increasing paracellular permeability in the intestinal barrier and exacerbating DSS- induced colitis in mice." (PMID 41359687, 2025).
colitis (continued). "The relative mRNA expression of tight junctions Claudin1, Occludin, and ZO-1 was also significantly reduced in DSS-induced colitis mice, while Rg1 significantly upregulated their relative mRNA expression and Rg3 significantly upregulated the relative mRNA expression of ZO-1." (PMID 40227284, 2025). "Isobutyric acid pretreatment significantly downregulated pro-inflammatory gene expression (IL-1β, TNF-α, NLRP3, and ASC) while upregulating tight junction components (occludin, claudin-1, and zo-1), demonstrating its protective role against DSS-induced colitis." (PMID 41171006, 2025). "However, the detection of the barrier protein Occludin and inflammatory factors TNF-α and IL-1β indicate the occurrence of colitis in the DSS + ABX mice." (PMID 40647020, 2025). "While occludin reactivity was significantly decreased in the colitis group compared to the control group (p < 0.001), it was significantly higher in the DHA group than in the colitis group (p < 0.001)." (PMID 39105785, 2024). "The elevated protein levels of MUC2, ZO-1, and occludin were further confirmed using Western blot, suggesting that ZW3 could improve the physical structure of the intestinal barrier during colitis." (PMID 38203732, 2024). "Furthermore, increased expression of occludin and ZO-1 was found to enhance the intestinal barrier in DSS-induced colitis mice." (PMID 39529667, 2024). "Additionally, sinapic acid exhibited a positive effect on colonic claudin-1, occludin, and ZO-1 in Kunming mice with DSS-induced colitis." (PMID 38732594, 2024). "Also, they enhanced the levels of occludin and VEGF in treated IBD murine, suggesting their capacity to alleviate colitis by supporting intestinal integrity and mucosa repair." (PMID 36707899, 2023). "Injury to epithelial cells is a colitis-initiating event that can increase epithelial barrier permeability; therefore, we examined the expression levels of Zo-1 and occludin, which were not affected by insulin treatment." (PMID 37491256, 2023). "Polysaccharides could inhibit the decrease in ZO-1 and Occludin gene expression in LPS-stimulated Caco-2 cells, thereby maintaining the intestinal epithelial integrity in DSS-induced colitis mice." (PMID 38139262, 2023). "Determination of occludin and Zonula occludens-1 (ZO-1) also indicated a significant decrease in the DSS-induced mice colitis group, while the effects could be relieved by giving the drugs of matrine to mice (P < .05)." (PMID 37326155, 2023). "Probiotics could effectively enhance the expression of sIgA, ZO-1 and Occludin in colon and improve intestinal microbiota dysbiosis to ameliorate MPA-induced colitis." (PMID 37533828, 2023). "In the present study, we observed the destruction of OCLN and ZO-1 in TNBS-induced colitis." (PMID 35571126, 2022). "In addition, the administration of loganin and morroniside as the physiological components of C. fructus prevented epithelial barrier injury by increasing the expression of Muc2, ZO-1, claudin-3, occludin, and E-cadherin in DSS-induced colitis." (PMID 36613533, 2022). "PSG significantly reduced the colonic inflammation by reversing the levels of myeloperoxidase, diamine oxidase activity, iNOS, and COX2 and strengthened the intestinal barrier by increasing the expressions of ZO1, occludin, and MUC2 of IBD mice." (PMID 36017235, 2022). "Extensive studies have shown that HFD dysregulates tight junction barrier protein expression (ZO-1, claudin, occludin) with or without experimental colitis in ileum and colon tissues of many rodents." (PMID 35887011, 2022). "In the inflamed colon tissue, we observed large absence of ZO-1 and occludin in DSS-induced colitis rats." (PMID 33722292, 2021). "Moreover, miR-34 in combination with long non-coding RNA PlncRNA1 cooperatively regulated the expression of occludin and ZO1 in Caco-2 monolayers undergoing DSS-induced colitis." (PMID 34943865, 2021).
colitis (continued). "In addition to IL-6 and IL-1β, earlier studies reported TNF-α-induced epithelial barrier dysfunction in rat colon via downregulation of occludin and E-cadherin and in DSS-induced colitis in mice." (PMID 33669494, 2021). "CD–Cur improved the protein expression of ZO-1 and occludin in DSS-induced colitis partially, but not significantly." (PMID 34121560, 2021). "The decreased expression of tight junction proteins (ZO-1, OCLN, and CLDN1) in colon tissues of colitis mice challenged by TNBS was enhanced by YST treatment, indicating the defective colonic mucosal barrier could be restored by YST." (PMID 34055024, 2021). "Oral BA (100 mg/kg) could enhance mRNA expression levels of ZO-1 and occludin in 2,4,6-trinitrobenzene sulfonic acid (TNBS)-induced colitis rats." (PMID 35059326, 2021). "The results from RT-qPCR analysis showed that DSS treatment induced a clear alteration in the mRNA expression level of tight junction complex ZO-1, E-cadherin and Occludin, however, and it was enhanced in DSS-treated colitis mice orally administered with QCWZD." (PMID 34557102, 2021). "Interestingly, administration of Ts-EVs increased occludin and ZO-1 expression and protected against epithelial junction damage in the TNBS-induced colitis model, thereby contributing to maintain the integrity of the intestinal barrier." (PMID 32595641, 2020). "With western blot and immunofluorescence, we found that the protein levels of occludin, claudin-1, and ZO-1 were reduced in DSS-induced colitis colonic tissues, and the reduction in miR-155 levels by miR-155 antagomir treatment increased the expression of these proteins (P<0.01)." (PMID 32713852, 2020). "In addition, occludin (OCLN), which plays a critical in maintaining intestinal barrier function, was decreased in colorectal tissues of ArgmyeKO mice during colitis." (PMID 32391010, 2020). "In CerS2-knockout (ko) mice, depletion of very-long chain ceramides is connected with disruption of the membrane integrity by downregulation of tight junction protein occludin and zonula occludens-1 (ZO-1), leading to enhanced severity of AOM/DSS-induced colitis in these mice." (PMID 31277430, 2019). "In addition, a previous study showed that propionate inhibited the expression of ZO-1 and Occludin and improved the intestinal barrier function in mice with DSS-induced colitis." (PMID 31141995, 2019). "In rats treated with dextran sulfate sodium, which has been widely used as a model for inducing acute and chronic colitis, a probiotic mixture of strain VSL#3 was shown to protect against increased intestinal permeability by up-regulating of expression of occludin, ZO-1, and claudins 1–5." (PMID 31623229, 2019). "The expression levels of these TJs in pretreated-Bifico-colitis and pretreated + treated-Bifico-colitis groups were extensively increased compared with the colitis group (P1 < 0.05 and P2 < 0.05 for JAM-1, P1 = 0.073 and P2 < 0.01 for occludin, and P1 = 0.598 and P2 < 0.05 for claudin-4)." (PMID 29849501, 2018). "Geniposide ameliorates inflammation and mucosal damage in colitis, which is correlated to regulation on nuclear factor kappa B, peroxisome proliferator-activated receptor γ and MCL2 pathways and the expressions of ZO-1 and occludin." (PMID 30618733, 2018). "The maggot protein could markedly restore expression of occludin and ZO-1 in mice with DSS-induced colitis." (PMID 30393231, 2018). "Furthermore, expression of occludin and ZO-1 protein in mice treated with DSS was clearly decreased as a result of acute colitis." (PMID 30393231, 2018). "DNBS-induced colitis was also characterized by an impairment of intestinal barrier function, as observed by evaluation of the different markers involved in the maintenance of epithelial integrity such as the mucins MUC-2 and MUC-3, occludin, and ZO-1." (PMID 28957373, 2017).